GSS (glutathione synthetase)
Diseases named in the same sentence as GSS in open-access papers (continued):
Sharing a sentence is not in itself a finding about the gene and the disease.
ischemic stroke (1 paper, 2022). A stroke disorder caused by obstruction of blood flow to the brain, due to thrombotic (local blood clot formation) or embolic (due to a blood clot or other material traveling from another site) event. "The present and previous studies clearly show that polymorphisms of key genes involved in glutathione biosynthesis such as GCLC, GCLM, GSS (glutathione synthase), and GGCT (gamma-glutamylcyclotransferase) are important contributors to the pathogenesis of ischemic stroke." (PMID 35455093, 2022).
leukemia (1 paper, 2024). A malignant (clonal) hematologic disorder, involving hematopoietic stem cells and characterized by the presence of primitive or atypical myeloid or lymphoid cells in the bone marrow and the blood. "Niclosamide, having a higher affinity for GSS due to its lower binding energy, competitively binds to GSS in leukemia cells, reducing the binding of GSS to ATP, thereby decreasing GSH synthesis and promoting ROS accumulation." (PMID 39060524, 2024).
liver disorder (1 paper, 2022). A disease involving the liver. "Ophthalmate is generated through consecutive reactions with γ-glutamylcysteine synthetase and glutathione synthetase; therefore, it is thought to be a biomarker of oxidative stress caused by a lack of glutathione, especially from liver disorders." (PMID 35323646, 2022).
lung adenocarcinoma (1 paper, 2022). A carcinoma that arises from the lung and is characterized by the presence of malignant glandular epithelial cells. "These investigators also found downregulation of GSS gene in in A549, ACE2-induced A549, Calu3 (lung epithelial cells derived from lung adenocarcinoma) cells infected with SARS-CoV-2-infected and in lung biopsy from SARS-CoV-2-infected patients." (PMID 35680931, 2022).
lung carcinoma (1 paper, 2024). "The decreased transcription of GCLC and GSS through the inhibition of NRF2 emerged as a mechanism of mutant EGFR/T790M resistance to EGFR inhibition in lung cancer." (PMID 39001381, 2024).
melanoma (1 paper, 2019). A malignant, usually aggressive tumor composed of atypical, neoplastic melanocytes. "First, we found that treatment of patient-derived melanoma CTCs with hydrogen peroxide (H2O2) (0–25 μM)—a major component of ROS—caused a dose-dependent increase of NRF2 target gene expression along with downstream anti-oxidant CAT, GSS, and TXNRD1 effector genes." (PMID 31003475, 2019).
neuroblastoma (1 paper, 2006). Neuroblastoma (NB) is the most common solid, extracranial childhood tumor. "Interestingly, when compared with neuroblasts, the neuroblastomas have more genes in common with the self-renewing neural stem cells (535 versus 145), among others the neurogenesis genes ASCL1, GSS, STAT3, UTP11L, ENAH, APBB2, CDK5RAP2, and LARGE." (PMID 16989664, 2006).
osteosarcoma (1 paper, 2020). A usually aggressive malignant bone-forming mesenchymal neoplasm, predominantly affecting adolescents and young adults. "Further dissection of the second enzyme of GSH synthesis, GSH synthetase (GSS), indicated that GSS was elevated in propagating osteosarcoma stem-like/progenitor cells." (PMID 32973147, 2020).
pulmonary TB (1 paper, 2020). "We also found increased plasma expression of glutathione synthetase (GSS) in pulmonary TB and glutathione Peroxidase-1 (GPX1) in patients with COPD." (PMID 33023021, 2020).
pyelonephritis (1 paper, 2019). An inflammatory process affecting the kidney. "MMP-8 and GSS mRNA levels were increased in 12 samples in patients with pyelonephritis 3.27 (p < 0.01) and 1.94 (p < 0.001) times, respectively." (PMID 31881666, 2019).
Renal cyst (1 paper, 2024). A fluid filled sac in the kidney. "Levels of GSH biosynthetic enzymes were also downregulated in renal cysts, including the catalytic subunit of the rate-limiting enzyme glutamyl cysteine ligase (GCLC, −2.5×), glutathione synthetase (GSS, −1.9×), and glutathione reductase (GSR, −2.3×)." (PMID 39000280, 2024).
uremia (1 paper, 2019). A clinical syndrome associated with the retention of renal waste products or uremic toxins in the blood. "Alhamdani evaluated the glutathione biosynthetic pathway in advanced uremia and hemodialysis measuring GSH levels and γ-glutamyl cysteine synthetase (γ-GCS) and glutathione synthetase (GSH-S) activities in nondialysis, hemodialysis, and continuous ambulatory peritoneal dialysis patients." (PMID 31089418, 2019).
Zinc deficiency (1 paper, 2024). A deficiency of the essential metal Zinc; an essential cofactor for many enzymes. "In agreement, several enzymes involved in ROS detoxification were induced in F. pedrosoi under zinc deficiency: catalase, glutathione reductase, glutathione synthetase, glutathione-S-transferase, and Fe/Mn superoxide dismutase." (PMID 38392790, 2024).
tumor (22 papers, 2014 to 2025). "The increase in GSH levels, glutathione synthetase (P48637), and glutathione S-Transferase (P09211, P78417, P21266) expression is associated with drug resistance in tumour cells." (PMID 33750814, 2021). "Lastly, we considered whether the compensatory Pvt1a upregulation, observed in gSS and Pvt1bP/P mutants, might account for the moderate effects of Pvt1b-deficiency on Myc levels, cellular senescence, and tumor growth." (PMID 40743223, 2025). "Overexpression of glutathione synthase (GSS) rapidly increases the flux from cysteine to reduced GSH to support tumor development by scavenging excessive ROS and maintaining them at lower cytotoxic levels to promote CRC progression." (PMID 40075600, 2025). "Our findings demonstrate that Vorinostat significantly suppresses phosphorylation of the PI3K/Akt signalling pathway and downregulates GSS expression, thereby inhibiting tumour progression both in vitro and in vivo." (PMID 41431124, 2025). "In this regard, the thiol status of tumors aligns perfectly with enzyme abundances, as both GSH synthesis (e.g. GSS) as well as the extracellular GSH scavenging enzymes (GGT1/5) were prominently upregulated in tumor tissue." (PMID 40461450, 2025). "A recent study found that ATRA had potent activity in eliminating MDSCs by specifically up-regulating gene expression and protein level of glutathione synthase (GSS) in MDSCs, leading to their differentiation into mature myeloid cells in tumor-bearing mice." (PMID 36081407, 2022). "Considering prior reports that HDAC inhibitors can suppress tumour cell proliferation and invasion, we postulated that Vorinostat might be a potential agent targeting GSS function." (PMID 41431124, 2025). "Western blot showed increased expression of glutathione synthetase in cells in culture compared to orthotopic or flank D425MED tumor and normal cerebellum, which was consistent with an increased glutathione production in cells in culture compared to orthotopic or flank tumors." (PMID 35267619, 2022). "HI tumors exhibit intermediate glutamate levels, which may indicate an enhanced uptake of this amino acid into the TCA cycle but also higher glutathione synthase (GSS) activity as these tumors also have higher GSH than the other tumor types." (PMID 35299741, 2022). "In pan-cancer analysis of 32 cancer species, ABCC1, CHAC1, and GSS may act as hallmarks to activate tumor immune reactions and reshape the tumor environment in LGG, LIGC, BRAC, LUAD, LUSC, and UVM." (PMID 34386492, 2021). "Moreover, doxorubicin treatment reduces the expression of the genes GCLC and GSS, respectively, in treated tumor cells over untreated tumor cells." (PMID 24565113, 2014). "Molecular analysis of tumour tissues revealed that the combination group exhibited significantly reduced protein levels of p‐AKT and GSS, accompanied by decreased FDX1 and increased HSP70." (PMID 41431124, 2025). "We next examined the effect, in tumor cells, of NCF-1 expression on the intracellular levels of regulators (glutathione synthetase (GSS) and glutathione peroxidase 4 (GPX4)) and a mediator (glutathione (GSH)) of ROS production." (PMID 39666242, 2024). "The sensitizing effect of H2O2 that has passed the cell membrane through aquaporins can be completely mimicked through pretreatment of the tumor cells with (i) BSO, an inhibitor of glutathione synthetase or (ii) with sulfasalazine, an inhibitor of the xC transporter." (PMID 34679719, 2021). "In detail, the estimated IC50 levels of cisplatin were distinctly lower in low expression than in high expression of GSS, GMPPA, and OGDH, suggesting that these three genes could be used as biomarkers whose low expression indicates the tumor is more sensitive to cisplatin." (PMID 35004676, 2021).
cancer (19 papers, 2013 to 2025). A tumor composed of atypical neoplastic, often pleomorphic cells that invade other tissues. "For the clinic use, we screened 75 FDA-approved cancer drugs and found that Fludarabine phosphate could decrease the expression of GSS and NFS1 most." (PMID 35067161, 2022). "The results showed that certain genes (such as GPX4, SLC7A11 and GSS) displayed higher expression, while others (such as ACSL1 and ACSL4) displayed lower expression in some cancer types." (PMID 34975326, 2022). "The effects of solasonine on glutathione metabolism, including GPX4 as well as glutathione synthetase (GSS), and inhibition of GPX4-induced ferroptosis are effective therapeutic strategies for triggering cancer cell death." (PMID 35494004, 2022). "Glutathione synthetase (GSS), which plays a key role in metabolism, catalyzes the last step of glutathione (GSH) synthesis, which is an important antioxidant that protects cancer cells against potential ferroptosis." (PMID 34386492, 2021). "Furthermore, targeting regulators of ferroptosis, such as AIFM2, glutathione synthetase (GSS), GPX4, FA complementation group D2 (FANCD2), and MAF BZIP transcription factor F (MAFF) can sensitize specific cancers to radiotherapy-dependent ferroptosis." (PMID 38844964, 2024). "To identify the drugs which could have a synergetic effect with ferroptosis-inducers, we screened 75 FDA-approved cancer drugs and found that fludarabine phosphate (F-ara-A) inhibited NFS1 and GSS expression most." (PMID 35067161, 2022). "In an in vitro study, the expression of the genes glutamate cysteine ligase (GCLC) and glutathione synthetase (GSS) that synthesize GSH and GSH-Px gene were verified by qPCR and subjected to treatment with doxorubicin, to check the resistance of cancer cells to chemotherapy." (PMID 24565113, 2014). "However the enzymes in the GSH pathway, namely glutathione synthetase (GSS) and Gamma-glutamylcysteine synthetase (GCLM) are ubiquitous and therefore selective targeting of GSH in cancer cells has remained a major clinical challenge." (PMID 24236104, 2013). "GCLC and glutathione synthetase (GSS), whose genes were identified by our analysis to be highly overexpressed in cancers and to confer bad prognosis in patients, are both essential enzymes catalyzing the synthesis of glutathione from glutamate, cysteine and glycine." (PMID 24342878, 2013).
infection (5 papers, 2007 to 2023). The state of being infected such as from the introduction of a foreign agent such as serum, vaccine, antigenic substance or organism. "It is important to note that the glutathione synthetase and reductase are increased at earlier times of infection (~3–6 h) when an increase in the reduced glutathione levels are observed again with P. gingivalis and ATP." (PMID 28725637, 2017). "Examination of the mRNA expression of key enzymes in the glutathione synthesis pathway displayed a marked increase (p < 0.05) in glutamate cysteine ligase (GCL) subunits GCLc and GCLm, glutathione synthetase, and glutathione reductase during the infection." (PMID 28725637, 2017). "Moreover, the second step in glutathione synthesis requires glutathione synthetase which is significantly increased by P. gingivalis at 3 h post-infection and reduced at 24 h." (PMID 28725637, 2017). "Among them were two glutathione synthases (GSS) responsible for the synthesis of glutathione, which had log2FC (3 DPI vs CK) values of 2.44 and 2.06, respectively, indicating up-regulation of the glutathione metabolism at the intermediate infection stage versus the CK." (PMID 37330505, 2023).
GSS also shares sentences with these, for which no sentence is quoted: Diabetes (2 papers); endometrial cancer (2); esophageal cancer (2); metabolic disease (2); 5-oxoprolinase deficiency (1); Alzheimer disease (1); anemia (1); astrocytomas (1); Ataxia (1); bacterial infection (1); breast tumors (1); chronic granulomatous disease (1); communicating hydrocephalus (1); cyst (1); depression (1); dyslexia (1); gastric cancer (1); hemoglobinopathies (1); Hypertension (1); kidney inflammation (1); myopathy (1); nephropathies (1); nephrotic syndrome (1); non-small cell lung carcinoma (1); Oral Squamous Cell Carcinoma (1); propionic acidemia (1); psoriasis (1); renal carcinoma (1); spinocerebellar degeneration (1).